LINC02571 (long independently transcribed non-coding RNA 2571)
Gene: Long non-coding RNA gene on chromosome 6 (31,293,908 to 31,301,642, reverse strand). Ensembl gene ENSG00000256166.
Diseases named in the same sentence as LINC02571 in open-access papers:
LINC02571 is named in the same sentence as 1 disease in open-access papers, as found by Europe PMC text mining. Sharing a sentence is not in itself a finding about the gene and the disease. The quoted sentences say what the papers report.
vitiligo (1 paper, 2022). Generalized well circumscribed patches of leukoderma that are generally distributed over symmetric body locations and is due to autoimmune destruction of melanocytes. "For example, WASF5P and LINC02571 have both been reported to be significantly associated with vitiligo in the Chinese Han population by GWAS." (PMID 36510243, 2022).